ERCC1 (ERCC excision repair 1, endonuclease non-catalytic subunit)
Diseases named in the same sentence as ERCC1 in open-access papers (continued):
Sharing a sentence is not in itself a finding about the gene and the disease.
cervical carcinoma (continued). "CAIX and ERCC1 were expressed more than the other three proteins in early cervical cancer tissues." (PMID 34350111, 2021). "In conclusion, the present study used immunohistochemical staining to validate how the expression of BCL-2, HER2, CD133, CAIX, and ERCC1 could predict chemoradioresistance and disease recurrence in patients with early cervical cancer." (PMID 34350111, 2021). "HER2, CAIX, and ERCC1 may be useful as predictive markers in chemoradioresistance and prognostic markers in the recurrence of cervical cancer." (PMID 34350111, 2021). "Furthermore, high HER2 expression predicted an unfavorable oncologic outcome, and low CAIX and high ERCC1 expression predicted an unfavorable response to adjuvant treatment in patients with early cervical cancer." (PMID 34350111, 2021). "A recent study analyzed the expression of XRCC1, ERCC2, ERCC4 and ERCC1 in cervical tissue samples and showed that the levels of both mRNA and protein were lower in squamous intraepithelial lesions and cervical cancer samples than in samples from control patients." (PMID 30674977, 2019). "Our aim was to explore whether ERCC1 expression predicted tumor response and survival in patients with recurrent or metastatic cervical cancer treated via platinum-based chemotherapy." (PMID 29390553, 2017). "Thereafter, several studies tested ERCC1 as a possible marker of resistance in cervical cancer." (PMID 28659181, 2017). "ERCC1 expression and the ERCC1 N118 N polymorphism remained independent predictors of the PFS after the performed multivariate survival analysis, thus rendering them significant prognostic factors in this metastatic or recurrent cervical cancer population." (PMID 28659181, 2017). "In this review, ERCC1 expression was found to be correlated to chemotherapy-resistance (i.e., cisplatin and 5-FU) in cervical carcinoma, chemotherapy combined with ERCC1 inhibitor may dramatically reduce the immunosuppression and thus reinstate the immune function." (PMID 36713431, 2022). "Affected genes and signaling pathways might contribute to the effects of ERCC1 in cervical cancer." (PMID 36713431, 2022). "Several studies have explored whether ERCC1 status is a useful marker of cervical cancer prognosis." (PMID 29390553, 2017). "The allelic frequencies of ERCC1 in cervical cancer patients were not significantly different from those of the controls in this study (P = 0.925)." (PMID 36713431, 2022). "Of note, some studies have also shown that ERCC1 expression does not have a clinical significance in patients with cervical cancer." (PMID 36713431, 2022). "As a result of this study, it was suggested that ERCC1 was not an essential component of the cervical cancer process." (PMID 36713431, 2022). "When ERCC1 expression at the mRNA and protein levels was assessed by northern and western blotting, respectively, in a panel of cervical carcinoma cell lines, there was a significant correlation between ERCC1 mRNA – but not ERCC1 protein – levels and cisplatin resistance." (PMID 18362936, 2008). "Thus, ERCC1 inhibitor combined with either traditional regimens (i.e., chemotherapy or radiotherapy) or lately immunotherapies (i.e., anti-PD1, anti-CTLA4, or both) may obtain promising antitumor efficacy on cervical cancer." (PMID 36713431, 2022).
cervical carcinoma (continued). "The specificity of this antibody was although recently challenged, since 8F1 stained a second spurious band on immunoblots from human fibroblasts but not HeLa cervical carcinoma cells and could not discriminate between ERCC1-positive and negative fibroblasts on immunofluorescence." (PMID 21961533, 2011). "However, ERCC1 expression showed a strong negative correlation with PFS and OS in this metastatic cervical cancer cohort." (PMID 28659181, 2017).
esophageal cancer (17 papers, 2008 to 2025). A primary or metastatic malignant neoplasm involving the esophagus. "This is the first study to investigate this regional population of Chinese with ESCC, and linked ERCC1 polymorphism to esophageal carcinoma in these patients that impacted overall survival." (PMID 25191856, 2014). "Although the link between platinum-based chemotherapeutics and ERCC1 is debatable, the predictive aspect of assessing ERCC1 polymorphisms is attractive for assessing risk of cancer development in esophageal cancer due to the high latency of detection and resulting poor outcomes in this disease." (PMID 25191856, 2014). "For example, S. Kirkilevsky found that the expression of miRNA-200b and ERCC1 in EC cells can be used to predict the aggressiveness of esophageal cancer, which was published in 2020." (PMID 37268893, 2023). "Polymorphisms of ERCC1 and XPF have been reported in Chinese patients with esophageal cancer, potentially influencing clinical outcomes following platinum-based chemotherapy." (PMID 29739952, 2018). "On the other hand, the ERCC1 protein is known to be overexpressed in human head and neck squamous cell carcinoma and esophageal carcinoma." (PMID 27410681, 2016). "Our findings are interesting as some of the data counter recent reports of the predictive ability of ERCC1 expression and treatment outcome and survival of patients with esophageal cancer." (PMID 25191856, 2014). "Two commonly studied ERCC1 SNPs occur at loci C8092A and C118T, and both have been suggested to predict treatment response or patient outcome in esophageal cancer." (PMID 25191856, 2014). "A relationship between the expression of ERCC1 and tumour response or survival was also reported in oesophageal cancer patients treated with chemoradiotherapy." (PMID 18594541, 2008). "In addition, we could not validate the findings of the previously published candidate gene study on ERCC1 (rs11615 and rs3212986), ERCC2 (rs13181 and rs1799793), and SLC22A2 (rs316019) in our head and neck and esophageal cancer discovery cohort." (PMID 34834585, 2021). "The expression levels of ERCC1, TYMS, TUBB3, RRM1 and TOP2A were determined using a microarray technique, while Spearman’s rank correlation analysis was used to determine the strength of the correlations between the expression levels of the biomarkers and the pathogenesis of esophageal cancer." (PMID 24926347, 2014). "Interestingly, no studies have investigated the relationship between ERCC1 and histopathological and clinical characteristics of esophageal cancer." (PMID 25191856, 2014).
lung adenocarcinoma (17 papers, 2009 to 2025). A carcinoma that arises from the lung and is characterized by the presence of malignant glandular epithelial cells. "Low ERCC1 expression has been associated with prolonged survival in lung adenocarcinoma patients treated with PMX as first line therapy." (PMID 39814799, 2025). "The aim of this study was to present our institutional observations regarding to the association of ERCC1 and overall survival (OS) of the lung adenocarcinoma patients who received chemotherapy based on platinum." (PMID 31521181, 2019). "Particularly in lung adenocarcinomas, ERCC1 has been shown to be associated with unchanged EGFR mutation status, to predict response to cisplatin-based therapies and also to be of prognosis value by itself." (PMID 25763322, 2014). "miR-138 is inversely correlated with excision repair cross-complementing rodent repair deficiency, complementation group 1 (ERCC1) expression in the A549/DDP multidrug-resistant human lung adenocarcinoma cells." (PMID 22954303, 2012). "In the multivariable Cox regression, ERCC1 118 variant genotype (CT/TT) remained prognostic factors of lung adenocarcinoma (HR = 1.60, P value = 0.001)." (PMID 20003463, 2009). "ERCC1 is known to be indispensable for the NER pathway, and it has been previously implicated with chemoresistance in lung adenocarcinoma." (PMID 39766117, 2024). "Novelty of the present study is that low ERCC1 expression is confirmed as a good predictive marker in all stages of lung adenocarcinoma in patients treated with platinum-based chemotherapy alone, or in combination with surgery or radiotherapy." (PMID 31521181, 2019). "ERCC1 expression in lung adenocarcinoma is a useful prognostic marker and moreover, a useful predictive marker in patients receiving chemotherapy based on platinum in all stages of the disease." (PMID 31521181, 2019). "Studies of excision repair cross-complementing gene 1 (ERCC1) expression have shown correlation with prognosis and response to treatment gastric, pancreatic, cervical, and lung adenocarcinomas." (PMID 25763322, 2014). "Comparison of cytologic with histologic scores showed similar mean values for breast and female genital tract carcinoma, whereas the lung adenocarcinoma controls had lower expression of ERCC1 compared with cytologic cores." (PMID 21961533, 2011). "We found that individuals carrying both ERCC1 118 and XRCC1 399 variant alleles were at a higher death risk of lung adenocarcinoma than those with only one of them (adjusted HRs were 2.44, 1.79 and 1.64, respectively)." (PMID 20003463, 2009). "In addition, other studies have reported a significant increase in the ERCC1 expression levels for lung adenocarcinoma patients in particular." (PMID 36558926, 2022). "Therefore, the aim of the study was to present our single-institution experience on the importance of ERCC1 analysis in lung adenocarcinoma patients." (PMID 31521181, 2019). "The results of many studies on the significance of ERCC1 in lung adenocarcinoma are inconsistent." (PMID 31521181, 2019). "Thus, further studies are needed to establish the role of ERCC1 in metastasizing lung adenocarcinomas." (PMID 26000095, 2015). "Napsin A, TTF-1, and ERCC1 are the markers indicating good prognosis of lung adenocarcinoma." (PMID 24667263, 2014). "This study aimed to investigate the association between the ERCC2 751, 312 and ERCC1 118 polymorphisms and the risk of lung adenocarcinoma in Chinese non-smoking females." (PMID 20003391, 2009). "To test above possibility, we assess the relationship between survival of lung adenocarcinoma patients and SNPs in three DNA repair genes, including excision repair cross-complementing group 1 (ERCC1) and group 2 (ERCC2), and X-ray repair cross-complementing group 1 (XRCC1)." (PMID 20003463, 2009). "Increasing numbers of either ERCC1 118 or XRCC1 399 variant alleles were associated with shorter survival of non-smoking female lung adenocarcinoma patients (Log-rank P < 0.001)." (PMID 20003463, 2009).
lung adenocarcinoma (continued). "In summary, our study sheds light on the relationship between polymorphisms in the DNA repair gene ERCC2 and ERCC1 with environmental risk factors and susceptibility to lung adenocarcinoma in nonsmoking females in northeast China." (PMID 20003391, 2009). "This study showed that being advanced stage, without chemotherapy or radiotherapy, carrying variant genotypes at ERCC1 Asn118Asn or XRCC1 Arg399Gln were proved to be unfavorable prognostic factors for lung adenocarcinoma in Chinese non-smoking women." (PMID 20003463, 2009). "The effect of the ERCC2 and ERCC1 polymorphisms, and also of the haplotypes encompassing these two genes, on susceptibility of lung adenocarcinoma in non-smoking females has not been reported so far." (PMID 20003391, 2009). "In human lung adenocarcinoma cell line A549, up-regulation of ERCC1 expression could be induced by low-dose cisplatin; in metastatic colorectal cancer, after oxaliplatin-based first-line chemotherapy, ERCC1 expression was upregulatedin." (PMID 25375151, 2014). "In the Cox regression model, after adjusting for age, tumor stage, surgical operation and chemotherapy or radiotherapy, variant genotypes of ERCC1 118 or XRCC1 399 polymorphism were associated with higher risks of death for non-smoking female patients with lung adenocarcinoma." (PMID 20003463, 2009). "In a recent study carried out by Li and co-workers, it was reported that ERCC1 overexpression inhibited the activation of the EGFR and stimulated resistance in lung adenocarcinoma cells to the combined therapy of cetuximab and cisplatin." (PMID 36558926, 2022). "The predictive value of ERCC1 was analysed by observing the correlation between OS of the lung adenocarcinoma patients in different TNM stages treated with different therapeutic modalities, and ERCC1 status." (PMID 31521181, 2019). "Therefore, we consider that H19 may play a major role in overcoming acquired resistance to cisplatin as a novel epigenetic regulator in lung adenocarcinoma such as ERCC1, and sensitizing H19 might be an efficient therapeutic intervention in cisplatin resistance of lung adenocarcinoma." (PMID 27911863, 2017). "This study aims to detect the expressions of Napsin A, TTF-1, ERCC1, RRM1, EGFR, HER2, ERα, ERβ, PR, and Bcl-2 in lung adenocarcinoma and to explore their correlations with clinicopathological characteristics and prognosis." (PMID 24667263, 2014). "Our data indicated that high ERCC1 expression is a valuable negative prognostic marker in patients with lung adenocarcinoma." (PMID 31521181, 2019). "In China, ERCC1 and XRCC1 were associated with the survival of non-smoker female lung adenocarcinoma patients." (PMID 23443124, 2012). "This study aimed to investigate the relationship between polymorphisms in ERCC2, ERCC1 and XRCC1 genes and survival of non-smoking female patients with lung adenocarcinoma." (PMID 20003463, 2009). "Using the stepwise Cox regression analysis, we found that the polymorphisms in ERCC1 and XRCC1, tumor stage and chemotherapy or radiotherapy status independently predicted overall survival of non-smoking female patients with lung adenocarcinoma." (PMID 20003463, 2009). "Genetic polymorphisms in ERCC1 and XRCC1 genes might be prognostic factors in non-smoking female patients with lung adenocarcinoma." (PMID 20003463, 2009).
testicular cancer (15 papers, 2008 to 2025). A primary or metastatic malignant neoplasm that affects the testis. "The hypersensitivity of testicular cancer to platinum‐based chemotherapy is associated with low abundance of ERCC1 and impaired DNA repair capacity." (PMID 33931939, 2021). "Excellent response to cisplatin in testicular cancer patients was explained by the inherent low ERCC1 expression in these tumours." (PMID 38272916, 2024). "Cell lines derived from cisplatin-sensitive testicular cancer, in which DNA repair is attenuated due to downregulation of ERCC1/XPF, undergo highly efficient apoptosis following cisplatin treatment." (PMID 37891379, 2024). "The relative risk (RR) of ERCC1, NF-κB, and TG2 for testicular cancer relapse after completion of chemotherapy are depicted in Figure-2." (PMID 32167697, 2020). "Specifically, low constitutive NER capacity and low levels of XPA, XPF and ERCC1 (NER proteins) have been reported in cisplatin-hypersensitive testicular cancer cells compared to other tumor types resistant to cisplatin." (PMID 27626685, 2016). "Testicular cancer, generally very responsive to CDDP, has low level of ERCC1, providing further correlative evidence for the importance of ERCC1 in CDDP resistance." (PMID 20470393, 2010). "Immunohistochemical analysis of ERCC1, NF-κB, and TG2 in patients with testicular cancer (n=50)." (PMID 32167697, 2020). "It has been known that intra-strand lesions, the primary type of DNA damage caused by CDDP are repaired by the nucleotide excision repair (NER) pathway and exquisite sensitivity to CDDP is observed in testicular cancer, which often presents with low expression of NER proteins, such as XPA and ERCC1." (PMID 26338199, 2015). "A previous study showed that high expression of ERCC1 was associated with non-sensitivity to cisplatin-based CT in patients with non-seminomas TGCT, but little is known about other mechanisms involved in platinum resistance in testicular cancer." (PMID 32167697, 2020).
head and neck cancer (14 papers, 2008 to 2025). A primary or metastatic malignant neoplasm affecting the head and neck. "ERCC1 C118T (rs11615) SNP was associated with increased risk of head and neck cancer in the overall population." (PMID 33266377, 2020). "Our results for ERCC1 concur with a study of head and neck cancer which reported that a low expression of ERCC1 was significantly associated with a complete response to cisplatin in the clinic." (PMID 31504065, 2019). "BZA treatment also markedly reduced chemo and radioresistance in head and neck cancer cells by downregulating ERCC-1, XRCC-1 and survivin expression." (PMID 28978005, 2017). "In fact, Bisof and coauthors have published that ERCC1 expression had no impact on overall survival in head and neck carcinoma patients treated with definitive radiotherapy (DR) or adjuvant radiotherapy (AR)." (PMID 24817012, 2014). "A study to determine whether DNA polymorphism of ERCC1 has predictive value in head and neck cancer patients showed that polymorphic variation in DNA repair genes (XPD and XRCC1, not ERCC1) is a powerful prognostic factor for the response to cisplatin in SCCHN patients." (PMID 18594541, 2008).